MDM2 (MDM2 proto-oncogene)
Diseases named in the same sentence as MDM2 in open-access papers (continued):
Sharing a sentence is not in itself a finding about the gene and the disease.
cancer (continued). "Similar to MDM2, spontaneous tumorigenesis was observed in mice overexpressing MDM4, and elevated expression of MDM4 or gene amplification has been described in a number of cancers." (PMID 27916892, 2016). "MDM2 [GenBank: AF527840] is amplified in 30–40 % of sarcomas as well as various cancers." (PMID 26293665, 2015). "Several reports describe MDM2 overexpression in certain cancers without gene amplification, such as leukemia, melanoma, and breast cancer." (PMID 26293665, 2015). "Despite the emerging role of MDM4 (structural homologue of MDM2) in the pathogenesis, maintenance, and chemo-resistance of human cancer, there are currently no selective MDM4 antagonists undergoing clinical trial evaluation." (PMID 26095524, 2015).
cancer (continued). "While alternatively spliced mdm2 messages have been detected in cancers, there is no documentation on endogenously produced polypeptides from such messages." (PMID 24147044, 2013). "A selective toxic effect of MDM2 inhibitors on cancer cells has been shown by other authors using a number of normal cell models." (PMID 23977270, 2013). "MDM2 inhibition reduces the expression of EMT markers and decreases the migration of cancer cells." (PMID 22911819, 2012). "Most of those experiments, if not all, were performed on cancer cell lines, where MDM2 is present and endogenous HSP70 levels are high." (PMID 23251530, 2012). "In our previous studies, we have shown that 25-OCH3-PPD inhibits MDM2 in cancer cells, although the detailed mechanisms are not fully understood." (PMID 22911819, 2012). "In some cases, even though there was no overall association noted with the MDM2 SNP309 and cancer susceptibility, substratification of groups led to some association." (PMID 20219101, 2010). "Cox multivariate analysis did not reveal modification of the MDM2 SNP309 effect on survival due to cancer onset age." (PMID 19226467, 2009). "We did not detect significant difference in cancer onset age in BRCA1/2 carriers harboring the different MDM2 SNP309." (PMID 19226467, 2009).
cancer (continued). "Recent progress in small molecule MDM2 inhibitors is discussed, with a focus on non-covalent agents such as rhein-derived anthraquinone analogs, including AQ-101, which demonstrate promising anti-cancer activity with reduced toxicity." (PMID 41749800, 2026). "Mutations in the MDM2 zinc finger, which disrupt its interaction with the 5S RNP complex, have been very useful in biochemical studies, but are exceedingly rare and unlikely to play a major role in cancer." (PMID 40427096, 2025). "Given that both MDM2 and STAT3 inhibitors have demonstrated promise in preclinical cancer studies, including those involving other hematologic malignancies, combined targeting of these two pathways may offer a more effective and safer treatment approach for ALL." (PMID 40943567, 2025). "Astragalin, which showed strong cytotoxicity against cancer cells, exhibited a non-significant difference compared to Nutlin in normal cells (p = 0.9796), suggesting a comparable safety profile to the reference MDM2 inhibitor." (PMID 40276802, 2025). "In addition, dinaciclib (CDK inhibitor), idasanutlin (MDM2 inhibitor inhibiting cell proliferation and inducing apoptosis), and romidepsin (HDAC inhibitor) were also very effective to reduce the T-PLL cancer cell viability, but these three drugs were only tested for the first T-PLL cohort." (PMID 41146244, 2025). "Elevated MDM2 transcript levels are also found in other cancers without gene amplification." (PMID 39498386, 2024).
cancer (continued). "Additionally, we demonstrate a negative correlation between MDM2 and miR-339-5p expression in human cancer, demonstrating the significance of the interaction for cancer." (PMID 36979159, 2023). "For example, BAX expression among cancer cells is lowest in upper aerodigestive lineages (UAD) and highest in fibroblast lineages; CDKN1A is lowest in blood and highest in fibroblasts; GDF15 is lowest in lymphocytes and highest in kidney; and MDM2 is lowest in thyroid lineages and highest in cervix." (PMID 36681780, 2023). "However, therapeutic reactivation of RUNX3 expression through epigenetic means may be insufficient to sustain RUNX3 expression as cancer progresses, as many UPS components, including E3 ligases such as MDM2 and Smurfs, are hyperactivated in cancer cells." (PMID 36899853, 2023). "No putative MDM2 amplification was detected in carcinoma samples." (PMID 38071286, 2023). "However, since the use of MDM2 inhibitors results in rather strong adverse effects, it might be clinically more interesting to target MDMX in cancer cells." (PMID 36139642, 2022).
cancer (continued). "As MDM2 can target pRb for either ubiquitin-dependent or ubiquitin-independent proteasomal degradation, MDM2 might potentially counteract HAUSP to affect pRb stability by either mechanism in cancer cells." (PMID 35650644, 2022). "Consequently, blocking MDM2 and MDM4 has been proposed as a cancer treatment strategy." (PMID 33669778, 2021). "However, MDM2 expression is not significantly different between cancer and paracancerous tissues in patients with NSCLC according to Western blot analysis results." (PMID 33612481, 2021). "Indeed, Nutlin blocks autophagy and promotes apoptosis in MDM2-amplified cancer cells, whereas it promotes autophagy in MDM2 non-amplified cells." (PMID 33406607, 2021). "In addition, NFAT1 acts as a novel transcription factor for the oncogene murine double minute 2 (MDM2) that is involved in the regulation of cell proliferation, cell cycle control, and apoptosis, suggesting the role of NFAT1 in cancer development, progression, and therapy." (PMID 34257525, 2021).